ODC1 (ornithine decarboxylase 1)
Diseases named in the same sentence as ODC1 in open-access papers (continued):
Sharing a sentence is not in itself a finding about the gene and the disease.
tumor (continued). "In this study, we found that the expression levels of SMOX and ODC1 proteins in tumor tissues of mice were significantly decreased after L.p CMU-Pb-L5 intervention." (PMID 39439459, 2024). "We also performed in vivo tumorigenicity assay by injecting 1000, 500, or 250 MDA‐MB‐231 NTC or ODC1/SRM knockdown subclone cells into SCID mice, and found that ODC1/SRM knockdown significantly decreased tumor‐initiating capacity." (PMID 39058337, 2024). "First, we knocked down ODC1 in Daoy cells and observed a significant decrease in the ability of tumour cells to invade and migrate." (PMID 38553479, 2024). "Targeting ODC1-mediated polyamine metabolism enhances immune cell infiltration in the tumour microenvironment, inhibits tumour cell dependence on polyamines, slows tumour growth and improves patient prognosis." (PMID 38553479, 2024). "OAT, AGMAT, and SMS are only up-regulated in tumor tissue (Fig. 3a9, a12, a17, b6, b8, and b10), while ODC1 and SRM are highly expressed in tumor and lymphoid tissues (Fig. 3a13, a15, b7, and b9)." (PMID 37164975, 2023). "Examples of regulated genes AMD1 and ODC1 in several cancers, notably PCa, and ODC1, are needed for tumor appearance, and overexpression indicates patient survival." (PMID 36834602, 2023). "For instance, ODC is overexpressed in most CRCs, and different tumor promoters induce ODC1 and tumor formation." (PMID 36900391, 2023). "The overexpression of ODC1 in multiple cancerous tissues contributes to tumor growth via generation of increased polyamines." (PMID 37308808, 2023). "ODC1 is an enzyme, which through overexpression has capacity to transform cultured cells, with uncontrolled proliferation and tumor formation as consequence." (PMID 36966162, 2023). "In oncology, it is thought that inhibiting the activity of ODC1 can regulate the synthesis of polyamines and thus inhibit the proliferation of tumor cells." (PMID 36998018, 2023). "An increase in enzymes controlling polyamine synthesis such as ODC1 leads to increased polyamines, which are thought to maintain the transformed phenotype and tumor development." (PMID 36457036, 2022). "Arg1 and Odc1 was reduced in cured mice (p < 0.05 for low dose BCG cured versus tumor bearing mice)." (PMID 34944584, 2021). "Odc1 promotes tumor growth by increasing availability of polyamines from ornithine and acts downstream from Arg1." (PMID 34944584, 2021). "Through upregulation of the cell cycle pathway and overexpression of NQO1 and ODC1, they exhibit an aggressive and chemoresistant tumor phenotype as well as a poorly differentiated histology." (PMID 32656360, 2020). "Activation of ODC1 and consequently increased concentrations of polyamines are related to tumor promotion and progression in many cancer entities." (PMID 32123240, 2020). "In this model, ODC1 ablation inhibited lymphomagenesis, but subsequent restoration of ODC1 activity promoted tumor onset." (PMID 23181218, 2012). "Inhibition of ODC1 by difluoromethylornithine (DFMO) decreased tumor penetrance in TH-MYCN mice treated pre-emptively, and extended survival and synergized with chemotherapy in treating established tumors in both TH-MYCN and xenograft models." (PMID 23181218, 2012). "ODC1 promotes tumor cell proliferation and mobility via the AKT/GSK3β/β‐catenin pathway." (PMID 40988561, 2026). "Targeting HOXB9 or ODC1 reduces polyamine levels and suppresses tumor growth/spread." (PMID 41402312, 2025). "At present, few researchers explored the role of ODC1 in the tumour immunotherapy response." (PMID 39189673, 2025). "Knockout of either HOXB9 or ODC1 suppressed HFD-induced subcutaneous tumor growth." (PMID 41402312, 2025). "Furthermore, HIF‐1α knockdown significantly decreased tumor‐initiating capacity in vivo, as measured by tumorigenicity assay, which was rescued by overexpression of ODC1 and SRM." (PMID 39058337, 2024). "Moreover, immunohistochemical analysis of Ki67, c-Myc, and ODC1 expression was conducted in subcutaneous xenograft tumor models." (PMID 38395945, 2024).
tumor (continued). "It has been suggested that the occurrence of ODC1-mediated polyamine metabolism in MB and the accumulation of polyamines may drive tumour development." (PMID 38553479, 2024). "Additionally, when exposing CD8+ T cells to conditioned medium collected from ODC1-knockdown cells, we observed an increase in both GzB and perforin, suggesting that tumor-derived polyamines affect functionality of CD8+ T cells." (PMID 39561012, 2024). "We, therefore, hypothesized that miR-378a was a potential tumor suppressor by repressing ODC1 and c-MYC expression." (PMID 36457036, 2022). "In addition, it is very difficult to measure ODC1 protein expression levels in tumor samples since ODC1 is a very low abundance protein and is highly regulated not only at the transcriptional level, but also by degradation." (PMID 33918978, 2021). "We therefore hypothesize that further genes of methyl group metabolism in addition to ODC1 contribute to disturbances of the methylome and thereby promote tumor progression." (PMID 32123240, 2020). "For example, a study about ornithine decarboxylase gene polymorphism (+316 ODC1 rs2302615) showed that age, gender, stage, colon/rectum site, tumor grade, and histologic subtype were not related to genotypes and alleles, with all p-values>0.05." (PMID 31350979, 2019). "Aggressive tumor behavior and poor outcome is correlated with high expression of synthetic genes (ODC1, SRM, SMS, AMD1, AZIN1) and low expression of catabolic genes (OAZ1, OAZ2, SAT1, PAOX), and these were identified as direct MYC effects by promoter activity and MYCN binding studies." (PMID 29799508, 2018). "Additionally, ODC1 itself has been shown to be amplified in ~6% of high-risk tumors along with MYCN and associates with exceptionally poor tumor survival (and unpublished data)." (PMID 29799508, 2018). "ODC1 was positive in the cytoplasm of the tumor cells (3 from 4 cases)." (PMID 22280838, 2012). "In addition, enforced expression of ODC1 in the skin of transgenic mice led to increased tumor incidence." (PMID 23181218, 2012). "The positive correlation of enzymes such as ODC1 and SRM in the polyamine pathway underscores the metabolic imbalances often associated with cancer, emphasising the complex network of metabolic interactions that can influence tumour progression and immune responses." (PMID 39457550, 2024). "Moreover, a variety of tumor promoters induces ODC1 and tumor formation." (PMID 30642111, 2019). "Lipid droplet staining indicated more lipid droplets in the tumor tissues of the HFD group, while knocking down HOXB9 or ODC1 reduced lipid droplet formation." (PMID 41402312, 2025). "First, the expression and biological functions of ODC1 and ALDH18A1 in tumor cells were confirmed through in vitro experiments, validation in several independent clinical samples has not yet been performed." (PMID 41573681, 2025). "Repeating the subcutaneous tumor model with sgRNA-mediated HOXB9 and ODC1 knockout cells yielded similar results." (PMID 41402312, 2025). "Treatment with an ODC1 selector inhibitor mitigates CSC enrichment, sensitizes tumors to cisplatin, and restricts tumor regrowth." (PMID 41271556, 2025). "In the subcutaneous xenograft tumor model, HFD promoted in situ tumor growth, whereas knockdown of ODC1 or HOXB9 attenuated this effect." (PMID 41402312, 2025). "They found a significant increase in the expression of polyamine-related genes ODC1, SRM, SMS, SAT1, and spermine oxidase in tumour-affected tissues." (PMID 39408925, 2024). "Western blot results similarly indicated that the expression levels of ODC1 and SMOX proteins in tumor tissues following L.p CMU-Pb-L5 intervention were significantly decreased compared with control group (P < 0.01)." (PMID 39439459, 2024). "When mice bearing ODC1-knockdown tumors were treated with systemic SPD, we observed a partial rescue of our original phenotype, indicating that tumor cell–derived SPD is a significant contributor of GBM progression." (PMID 39561012, 2024).
tumor (continued). "ODC1 activity is frequently elevated in cancer through deregulation of MYC, resulting in higher polyamine content to support rapid tumor cell proliferation." (PMID 36845724, 2023). "AR drives the expression of two key enzymes, ornithine decarboxylase (ODC1) and the SAM-decarboxylase AMD1, thus elevating polyamine to levels necessary for transformation and tumor progression." (PMID 36358940, 2022). "In tumor bearing mice CCL24, CD163 and MMP7 were upregulated after therapy and IL24 and Odc1 were downregulated (p > 0.05)." (PMID 34944584, 2021). "While ASS1 was found to be downregulated in GBM tumours and NCH644 NS cultures, the expression of ODC1, SLC25A13 and SLC25A15 was increased." (PMID 33809510, 2021). "Only the fold change in DDAH2, ODC1, and PRMT5 expression differed significantly with overall TNM stage, with tumor-to-adjacent ratio decreasing in a stepwise manner along with increasing stage." (PMID 32872669, 2020). "Ornithine decarboxylase (ODC1) and A-Raf proto-oncogene as well as serine/threonine kinase (ARAF), both upregulated by AFB1, play a role in tumor promotion." (PMID 32610656, 2020). "Significant hypermethylation of ODC1, MTHFR and AHCYL2 occured also in the tumor adjacent, histologically benign urothelial tissue samples." (PMID 29472622, 2018). "Therefore, knocking down HOXB9 or ODC1, or adding DFMO to drinking water effectively inhibits LNM as well as in-situ tumor growth, indicating a promising target for reversing of metabolic disorder promoted EC progress." (PMID 41402312, 2025). "Targeting ODC1 and HOXB9 inhibits tumor formation and LNM in xenograft models." (PMID 41402312, 2025). "Additionally, in the tumor tissues of EC patients with LVSI or LNM from 2014–2020, a significant correlation between HOXB9 and ODC1 (r = 0.56, p = 0.02) is demonstrated by IHC, indicating the association between HOXB9 and ODC1 at the protein level." (PMID 41402312, 2025). "ODC1, a key rate‐limiting enzyme, is a poor prognostic indicator for HCC and other tumours." (PMID 39189673, 2025). "Additionally, semi-quantitative analysis of positive cells in the tumor tissues revealed that the expression of SMOX and ODC1 in CMU-Pb-L5 group and 5-Fu group was significantly lower than that in control group (P < 0.001)." (PMID 39439459, 2024). "Our findings show that SPD itself, either increased via exogenous addition or reduced via ODC1 knockdown, did not alter intrinsic tumor growth but did impact cytotoxic T cells and Tregs." (PMID 39561012, 2024). "Immune phenotyping of mice implanted with ODC1-knockdown cells revealed an increase in the proportion of CD8+ T cells in the tumor microenvironment in comparison with non-targeting controls." (PMID 39561012, 2024). "Since ODC1 is an established MYC target gene, we investigated the possibility of differential effects of the SNP in subsets of patients depending on the MYCN status of their tumor." (PMID 33918978, 2021). "The expression of ODC1 was less downregulated in advanced cancers and a fold change in its expression correlated positively with TNM and lymph node metastasis and tended to correlate with the primary tumor extension as well." (PMID 32630408, 2020). "Immunohistochemistry also showed reduced SMOX and ODC1 protein levels in mouse tumor tissues after L.p CMU-Pb-L5 treatment, consistent with Western blot results, further supporting L.p CMU-Pb-L5's role in inhibiting tumor growth by suppressing polyamine synthesis." (PMID 39439459, 2024).
tumor (continued). "We also performed tumor eradication and recurrence assay by implanting MDA‐MB‐231 NTC or ODC1/SRM knockdown subclone cells into SCID mice, treating the mice with paclitaxel when tumors became palpable, terminating treatment when tumors were fully eradicated, and monitoring tumor recurrence." (PMID 39058337, 2024). "IHC staining of tumor and adjacent healthy tissues indicated up-regulation of the VDAC2, CSNK2A2, and MIF genes in tumor tissues, although the expression levels of ODC1 did not change, possibly because of the large differences in the positive signal values between the various samples." (PMID 37231440, 2023). "Similarly to ODC1, it resulted from gene downregulation in tumors with concomitant upregulation in tumor-adjacent noncancerous tissue." (PMID 32872669, 2020). "Furthermore, six tumor progression genes (GNAI2, ODC1, APP, TNFRSF12A, BASP1, and LARP6) and nine migration and metastasis‐related genes (MSN, FLOT1, LAMB3, MYL9, ITGB1, FTH1, TPM4, and PMEPA1), which could explain the invasive characteristics of SCC, were identified." (PMID 40776410, 2025). "Though our studies leveraged mouse models for the assessment of ODC function, we found that ODC1 expression was present across human GBM tumors, irrespective of tumor subtypes/states (data not shown)." (PMID 39561012, 2024). "Accordingly, ODC1 expression correlated positively with TJP1 in both non-cancerous and tumor tissue." (PMID 32630408, 2020). "ODC1/SRM knockdown did not alter time for tumor formation or tumor eradication, but significantly increased time for tumor recurrence, indicating that ODC1/SRM knockdown decreases numbers of BCSCs in response to paclitaxel treatment, which is a major cause of tumor relapse." (PMID 39058337, 2024). "Briefly, the tumor (N = 7) and adjacent (N = 6) tissues of OS patients were collected and stained using IHC, showing that CSNK2A2, VDAC2, and MIF were markedly upregulated in OS tissues compared with the control tissues, whereas the expression of ODC1 showed no significant change." (PMID 37231440, 2023).
cancer (110 papers, 2006 to 2026). A tumor composed of atypical neoplastic, often pleomorphic cells that invade other tissues. "ODC1, an oncogene involved in polyamine biosynthesis, is associated with poor prognosis when up-regulated in various cancers." (PMID 40225858, 2025). "Disturbances in polyamine homeostasis are closely linked to cancer development, with elevated polyamine levels and ODC1 expression observed in many epithelial tissue-associated cancers like CRC36." (PMID 39439459, 2024). "Several studies have earlier shown that one of the most important cancer-associated transcription factors that enhances ODC1 expression is MYC20." (PMID 36966162, 2023). "As another example, ornithine decarboxylase 1 (ODC1) (3-hop neighbor) was the topmost similar gene to the genetic risk for cancer." (PMID 35903362, 2022). "Increased polyamine synthesis has been linked to improving cancer survival and growth, with overexpression of ODC1 being associated with breast, lung, colon, prostate, pancreatic cancer, and others." (PMID 35955511, 2022). "Genetic polymorphisms within ODC1 are associated with outcomes in colorectal, gastric, breast, and prostate cancers." (PMID 33806076, 2021). "Accordingly, ODC1 expression in the colon is upregulated in conditions associated with increased risk of cancer." (PMID 32872669, 2020). "There are frequent mutations of one or more MYC genes in various cancers, and the overexpression of ODC1 is regulated by MYC activation." (PMID 33292222, 2020). "The associations with neurological phenotypes, in addition to the expected cancer and bone growth phenotypes, speak to a need to establish the mechanisms and direct connection of these variants to changes in ODC1 biology in multiple organ systems through systematic analysis." (PMID 33806076, 2021). "Similarly, ODC1, an enzyme involved in polyamine synthesis that has been implicated as an oncogene in numerous cancers, was also found to contain two hypomethylated regions in a 9.02kbp interval within intron 13 and was the target of an overexpressed miRNA, ssc-miR-27a." (PMID 40040391, 2025). "Subsequently, HOXB9 interacts with ODC1, preventing its degradation and leading to the accumulation of polyamines, thus promoting cancer progression." (PMID 41402312, 2025). "Our study suggests that OA’s up-regulation of ODC1 triggers polyamine accumulation and cancer progression, explaining the mechanism by which OA promotes EC and establishes the chain of OA-ODC1-polyamine-EC progression." (PMID 41402312, 2025). "Recently, emerging studies have demonstrated that ODC1 is aberrantly expressed and plays a vital role in cancer." (PMID 38553479, 2024). "M-E4BP4 showed increased expression of anti-inflammatory genes such as Retnla, IL10, and C1qa, and Ccl5, which is involved in immune escape of cancer, and decreased expression of pro-inflammatory genes such as Txnrd1, Odc1, Mmp1232,36–40." (PMID 38714733, 2024). "Ornithine decarboxylase 1 (ODC1), a crucial enzyme for polyamine biosynthesis using ornithine from the urea cycle, is frequently deregulated in cancer." (PMID 38238756, 2024). "DFMO has been utilized as an ODC1 inhibitor in various cancer models, yet in clinical use it has yielded limited results." (PMID 36966162, 2023). "For other cancer entities including bladder cancer and oral cavity carcinoma, a downregulation of ODC1 by DNA hypermethylation and subsequently global demethylation has been reported." (PMID 35955511, 2022). "In contrast, ODC1 expression is upregulated in many other cancer types, e.g., prostate, colon, and esophageal carcinoma show an elevated expression." (PMID 35163453, 2022). "The proto-oncogene MYC is highly overexpressed and/or amplified in human cancers and transcriptionally activates ODC1; thus, polyamine metabolism is an attractive cancer therapeutic target." (PMID 35736351, 2022).